STAT3 (signal transducer and activator of transcription 3)
Diseases named in the same sentence as STAT3 in open-access papers (continued):
Sharing a sentence is not in itself a finding about the gene and the disease.
cancer (continued). "The results showed that compared with the control, ART1-sh cancer cells induced by IL-6 exhibited reduced viability, a lower rate of colony formation, less DNA synthesis, decreased protein levels of gp130, c-Myc, cyclin D1, Bcl-xL, and a reduced p-STAT3/STAT3 ratio (P < 0.05)." (PMID 38504172, 2024). "Curcumin may reverse cancer progression through the inhibition of IL-6R/STAT3." (PMID 39061221, 2024). "Additionally, betavulgarin decreases the levels of proteins like c-myelocytomatosis (C-Myc), Nanog, and octamer-binding transcription factor 4 (Oct4), essential for self-renewal, and inhibits the Stat3/Sox2 signaling pathway, which is vital for cancer stem cell survival." (PMID 39682981, 2024). "Furthermore, CD109’s potential involvement in the IL-6/GP130/STAT3 axis, a key driver of chronic inflammation and cancer stem cell survival, suggests it may help sustain an inflammatory environment that fosters metastasis and immune evasion." (PMID 39990858, 2024). "Furthermore, the treatment of HCC-1954 cells with a STAT3 inhibitor alone significantly decreased short-term and long-term cancer cell survival, indicating that these cells may benefit from single-agent treatment with STAT3 inhibitors." (PMID 39001513, 2024). "Indeed, we discovered that 23-HBA decreased the phosphorylation level of STAT6 protein in M2 macrophages, accompanied by a decrease in M2-related cytokine IL-10 secretion and an inhibition of STAT3/Bcl-2 signaling of cancer cells, resulting in a reduction in 5-FU resistance." (PMID 38554148, 2024). "Interestingly, we also found that IL6Rα expression was negatively correlated with pSTAT3 response to IL-10, indicating that heightened IL6Rα and IL-6 in cancer patients may be dominating STAT3 signaling and in turn suppressing the IL-10 responsiveness." (PMID 39389979, 2024). "Thus, cancer cell-specific-targeting of JAK2/STAT3 or combinations with immunotherapy may be required for further evaluation of JAK2/STAT3 signaling as a cancer therapeutic target." (PMID 38297352, 2024). "PTEN is a tumor suppressor protein that may mediate STAT3’s variable role in cancer development." (PMID 38339245, 2024). "Deeper insights in the activities of STAT3 in ESCs may help further dissecting the molecular mechanisms regulating self-renewal and possibly unveiling novel molecular targets mediating STAT3-dependent pro-oncogenic activities, first and foremost the induction of a stem cell status in cancer cells." (PMID 37801430, 2024). "Thus, it is reasonable to hypothesize that CAF-secreted factors may act in a paracrine manner on neighboring carcinoma cells to activate STAT3, leading to the subsequent expression and secretion of GM-CSF." (PMID 39199680, 2024). "Therefore, targeted inhibition of STAT3 expression may have high research value for the development of combined immunotherapy/targeted therapy approaches for the treatment of cancer patients." (PMID 37724127, 2023). "Therefore, STAT3 may have high research value for the development of combined immunotherapy/targeted therapy approaches for the treatment of cancer patients." (PMID 37724127, 2023). "Of note, differently from NRF2, the activation of STAT3 can promote cell survival/proliferation, either during the first steps of carcinogenesis and in established cancer cells, also because its activation may be sustained by NF-κB, as in the case of glioblastoma." (PMID 37000324, 2023). "Thus, STAT3 has a leading role in cancer, inflammation, and immunity." (PMID 37994325, 2023). "Likewise, the activation of NF-κB by oxLDL/LOX-1-ROS could induce the secretion of IL-6 observed in our study, which in turn may act in an autocrine fashion to stimulate STAT3 signaling, as it has been observed in other types of cancer." (PMID 36982155, 2023). "Hence, STAT3 inhibition is considered a promising therapeutic anti-cancer strategy." (PMID 36760267, 2023). "Therefore, several treatment strategies target the STAT3 pathway for cancer therapy." (PMID 37375411, 2023).
cancer (continued). "Therefore, STAT3 has a passive role in maintaining the glycolytic flux in cancer cells." (PMID 37762231, 2023). "Thus, inhibitors targeting JAK/STAT3 have enormous potential for cancer treatment." (PMID 37103357, 2023). "Inhibition of one STAT3 isoform, while sparing the other, may improve cancer treatment outcomes." (PMID 37097001, 2023). "The results indicate that curcumin could effectively inhibit the growth and migration of hepatocarcinoma cells by inducing cancer cell apoptosis, blocking the cancer cell cycle in the S phase, and reducing the expression of STAT3, VEGF, and HIF-1α signaling pathways." (PMID 37333486, 2023). "Furthermore, mesothelial cells contribute to the creation of a tumor‐promoting niche by transitioning to cancer‐associated fibroblasts via mesothelial‐to‐mesenchymal transition and secreting factors including PAI‐1, which activates the oncogenic transcription factor STAT3 on cancer cells." (PMID 36700339, 2023). "Finally, STAT3 enhanced the immune escape of cancer cells in the presence of IL-10 and TGF-α." (PMID 36923251, 2023). "Interestingly, the inhibition of STAT3 in cancer may give the double advantage to impair cell survival and concomitantly reactivate the anti-cancer immune response." (PMID 37000324, 2023). "Thus, STAT3 is an attractive target for the development of new therapeutic targets in cancer." (PMID 36769245, 2023). "Therefore, inhibition of STAT3 signaling can restore cancer cells’ drug sensitivity." (PMID 37065872, 2023). "However, we identified that treatment of primary hepatocytes with C15:0 and C17:0 suppresses JAK2/STAT3 signaling, which may indicate an anti-cancer and anti-NAFLD effect of OCFA." (PMID 37432205, 2023). "In addition to the AKT pathway, other signaling pathways have also been reported to be involved in PDIA3-mediated biological functions in cancers, such as STAT3 signaling, EGFR signaling, 1alpha, 25-dihydroxy vitamin D3 [1,25(OH)2D3]-mediated pathway and mTOR signaling." (PMID 38213579, 2023). "In 2019, research revealed that verteporfin, by blocking YAP1 (a transcriptional regulator of genes that promote cell survival and proliferation) and STAT3, might become an appropriate medicine for targeted therapy of cancer stem cells (CSCs), which may be the promise of targeted therapy for BC." (PMID 37124495, 2023). "Interestingly, this effect was notably dampened in mice with STAT3 R729K mutant cancer cells." (PMID 37813837, 2023). "In addition, when co-cultured with human breast cancer cells, neutrophils produced high levels of oncostatin M (OSM), which was shown to act on the endothelium via STAT-3/VEGF signaling in vivo and to enable the remodeling of the TME by activating cancer-associated fibroblasts (CAF)." (PMID 37234993, 2023). "Therefore, targeting HSPs could allow to restore anti-cancer immune response, by interrupting the interplay between STAT3 and cytokine production." (PMID 36835344, 2023). "However, when STAT3 was constitutively activated, this resulted in high levels of LKB1/pAMPK and decreased activity of the mTORC1/CREB pathway, preventing the development of cancer in mice with PTEN loss." (PMID 37573301, 2023). "Five major targets in the treatment of cancer have been identified: human Aurora B kinase, phosphatidylinositol 3-kinase alpha (PI3Kalpha), the signal transducer and activator of transcription 3 (STAT3), protein kinase B (Akt), and c-kit tyrosine kinase (c-Kit)." (PMID 37259360, 2023). "Consequently, targeting STAT3 is viewed as a promising approach for treating cancer." (PMID 37046823, 2023).
cancer (continued). "Moreover, the result underpins that sugiol’s interactions with STAT3 may contribute to its inhibitory effects on cancer cell growth and proliferation." (PMID 38004394, 2023). "Additionally, the protein expression results showed that corosolic acid could hinder the activation of both JAK2 and STAT3 proteins within these cancer cells by inhibiting the phosphorylation and activation of these proteins." (PMID 37009004, 2023). "It was found that plumbagin affects the various signaling pathways involved in cancer cell proliferation, survival, invasion, and metastasis through suppression of some signaling molecules such as nuclear factor-kappaB (NF-κB) and signal transducer and activator of transcription 3 (Stat3)." (PMID 37110873, 2023). "Importantly, coexpression of IRF1 and STAT3 in ATXN3-KO cancer cells fully rescued IFN-γ–induced PD-L1 expression, but had little effect on hypoxia-induced PD-L1 expression, confirming that ATXN3 promotes IFN-γ–induced PD-L1 expression specifically through stabilizing IRF1 and STAT3." (PMID 38038129, 2023). "Interestingly, the IL-6/JAK/STAT3 and complement pathways were the most highly upregulated genes in Group 2, inferring an association with immune activation and cancer metastasis control, which is not reported in the BL2 subtype." (PMID 37334114, 2023). "However, in cancer models, inactivation of STAT3 actually leads to diminished CAC tumor growth." (PMID 38002302, 2023). "Therefore, finding a way to specifically target activation of STAT3 in cancer cells could be an appealing strategy." (PMID 37095176, 2023). "However, the specific molecular mechanisms of STAT3 in the pathogenesis of different tumors remain unclear, as is their value in the human pan-cancer analysis." (PMID 37724127, 2023). "STAT3, as an anti-cancer target, may exert immune activation rescue in the TME." (PMID 36816749, 2023). "Thus, inhibiting STAT-3 activity is an effective method for treating cancer." (PMID 37175040, 2023). "UA has also been suggested to inhibit proliferation signaling pathways including Ras/MAPK, PI3K/Akt, and STAT3, downregulate the apoptosis inhibitor X-linked inhibitor of apoptotic protein (XIAP), and suppress the transcription factor Sp1 (which is a poor prognostic factor for many cancers)." (PMID 37376594, 2023). "Taken together, pS727 STAT3 may represent a promising target in cancer immunotherapy." (PMID 37945711, 2023). "This complexity may lead to difficulties in using STAT3 as target for inhibition in cancer, adding to the inherent problems of high STAT3 sequence similarity to other members of STAT family, poor bioavailability and high toxicity of the currently proposed drugs." (PMID 37190183, 2023). "Due to the scarcity of published research in the field of LNK and luminal cancer, we conducted an analysis of the available datasets containing genetic data with the intention of shedding some light on the potential associations among LNK, JAK2, STAT3, STAT5, 14-3-3, and clinical outcomes." (PMID 37834225, 2023). "However, in cancer cells, it is unknown whether HLA-G activates STAT3 pathway via ILT4 or other yet unidentified protein partners." (PMID 36780531, 2023). "Additionally, cytokine produced by M2 macrophages could also directly act on HCC cells to transform them into cancer stem cells through IL16/STAT3 signaling pathway, and promote their migration by CCL22‐CCR4 interaction." (PMID 36680322, 2023). "Therefore, our study provides evidence for targeting STAT3 in cancer therapy." (PMID 37308559, 2023). "Indeed, hyperactivation of STAT3 has been reported in many cancers." (PMID 37561163, 2023). "However, the possibility that targeting ATXN3 in non-cancer cells may alter immune functions as a result of accelerated STAT3, IRF1, and HIF-2α degradation cannot be excluded." (PMID 38038129, 2023).
cancer (continued). "These compounds play a role in cancer protection through the modulation of various cell signaling pathways including inflammation, antioxidant potential, tumor suppression gene, apoptosis, angiogenesis, growth factor, signal transducer, activator of transcription 3 (STAT3) and other pathways." (PMID 36558146, 2022). "And MMP-2 and S100A4 may be the key targets of STAT3 involved in cancer metastasis." (PMID 35513871, 2022). "Considering the prominent functions of STAT3 in maintaining the characteristics of CSCs, it is reasonable to speculate that STAT3 inhibition can markedly or permanently eliminate CSCs for achieving cancer prevention." (PMID 36557902, 2022). "We test whether silencing STAT3 reverses the cancer-promoting effect of SENP3." (PMID 36227136, 2022). "Targeting STAT3 could be an effective way to repress the mitochondrial function in cancer cells." (PMID 36429126, 2022). "Also, the STAT3 molecule interacts directly with NF-κB and in the form of heterodimers goes to the nucleus where it affects the expression of the molecules which stimulates the proliferation of cancer cells." (PMID 35897737, 2022). "Pharmacological inhibition or shRNA-mediated depletion of STAT3 suppressed the NDV/FMW-caused ICD determinants, including HMGB1 and HSP70/90 release, CRT exposure, and ATP secretion, suggesting plausible mechanisms to fine-tune NDV-induced ICD in diverse cancer types." (PMID 36755812, 2022). "Furthermore, TAMs could mediate EMT to promote the migration and invasion of cancer cells, which is associated with activation of JAK2/STAT3/miR-506-3p/FoxQ1 axis." (PMID 35251963, 2022). "Therefore, the present study investigated whether blocking IL-6/IL-6R/STAT-3 signaling disrupts proliferation, migration, invasion and clonogenicity of PCa cells; these processes are essential to metastasis in cancer." (PMID 35703345, 2022). "Consequently, STAT3 proteins have been a key target for cancer therapy." (PMID 36542668, 2022). "Thus, we have identified a novel link between XRCC1 expression and STAT3 activation following exogenous exposures, which could play a critical role in dictating a cancer cell’s response to DNA-damaging agents." (PMID 35457130, 2022). "However, how apoptotic cancer cells activate significant STAT3 signaling in BM macrophages and how this signal is maintained remains to be elucidated where a potential amplification loop could be critical." (PMID 36496973, 2022). "Hence, “direct STAT3 inhibitors” could effectively suppress treatment-induced and multiple factors-mediated STAT3 activation as well as subsequent adaptive cancer cell survival." (PMID 35228642, 2022). "Finally, STAT3 plays a major role in energy metabolism for cancer cells." (PMID 35800364, 2022). "However, it may also be true that SAA regulates other signaling mechanisms, such as JAK/STAT3, that can regulate autophagy in cancer cells." (PMID 36248994, 2022). "Thus, the IL-6/STAT3 pathway appears to play a more complex role than just promoting cancer growth, even though several studies show a good correlation between activation of this pathway in epithelial cells and cancer progression." (PMID 35757757, 2022). "Accumulating evidence suggests that free radical overproduction and/or inability to effectively neutralize them, may promote chronic inflammation, a well-established cancer enabling characteristic, via Nuclear Factor kappa b (NF-kB), STAT3 and other molecular pathways." (PMID 35565732, 2022).
cancer (continued). "Interestingly, the high-risk score group also comprised significant enrichment of unfavorable cancer-related hallmark gene sets, such as “ANGIOGENESIS”, “E2F_Target”, “IL2_STAT5 signaling”, “IL6_JAK_STAT3 signaling”, “MTORC1 signaling”, “MYC_TARGETS_V1” and “PI3K_AKT_MTOR signaling”." (PMID 37304008, 2022). "Similar to many other crucial signaling pathways, those pathways that are linked to cancer cell proliferation and metastasis are regulated by multitudinous positive as well as negative signaling that is initially induced by over-activation of JAK/STAT3 pathways." (PMID 35852862, 2022). "Therefore, STAT3 signaling is a viable target for cancer therapy, and the use of its inhibitors may impede the progression of cancer." (PMID 36557902, 2022). "For instance, it has been demonstrated that the blockade of JAK2/STAT3 signaling pathway notably inhibits the protein levels of high mobility group box 1, an important mediator in the pathogenesis of many diseases, including arthritis, sepsis, cancer or autoimmunity diseases." (PMID 36004343, 2022). "Therefore, the STAT3 pathway is a promising target for cancer therapy." (PMID 35356799, 2022). "Furthermore, STAT3 upregulates STAT1 expression in cancer cells." (PMID 35806366, 2022). "In addition, STAT3 knockdown could effectively suppress cancer stem cell-like properties, synergistically enhance the effects of radiotherapy, and significantly improve the survival of immunocompromised mice." (PMID 35251963, 2022). "Moreover, STAT3 feedback activation might perform an important role in mediating drug resistance to a wide range of targeted cancer therapies and chemotherapies." (PMID 36557902, 2022). "Moreover, STAT3 is closely associated with IL-6, AMPK, or ERK in cancer progression." (PMID 35742904, 2022). "Interestingly, nicotine-mediated activation of both a5 and a9 nAChRs have been shown to upregulate PD-L1 expression in cancer cells via STAT3 signaling pathways, so a positive correlation of nAChRs with PD-L1 may be expected." (PMID 36072788, 2022). "Finally, STAT3 plays an important role in chemoresistance in cancer cells." (PMID 35800364, 2022). "We could confirm the expected limiting effects of the STAT3-KO on several hallmarks of cancer, including proliferation (analyzed by MTT assays), cell migration (analyzed by scratch migration assays) and cell invasion (analyzed by sphere invasion assays into matrigel)." (PMID 35053502, 2022). "Therefore, its suppression across HCC cells could suggest that the inhibitor of STAT3 may also suppress STAT3 (constitutively activated) in cells affected by other kinds of cancer." (PMID 36080130, 2022). "Furthermore, we established a direct link between Pdia4, Stat3 and Vegf family in cancer stroma." (PMID 35170261, 2022). "Therefore, a possible cancer treatment method is to degrade the STAT3 protein." (PMID 36142231, 2022). "Moreover, STAT3 could activate of NF-κB signaling pathway through mediating p100 process to p52, and this way was perceived to be a common pathway of representing cancer cells to survive and escape therapy." (PMID 36153596, 2022). "Collectively, our findings support the concept of exploiting the pro-death functions of autophagy and LMP for GBM therapy and to further determine whether STAT3 can be employed as a treatment predictor for highly apoptosis-resistant, but autophagy-proficient cancers." (PMID 35053502, 2022). "Therefore, STAT3 plays a role in the crosstalk between cancer and immune cells." (PMID 35936759, 2022). "Thus, targeting STAT3 phosphorylation using a small-molecule approach could be a potential strategy for chemoprevention and cancer therapy." (PMID 36080130, 2022). "Therefore, STAT3 inhibition helps preserve muscle mass in cancer cachexia." (PMID 35806366, 2022). "STAT3 inhibitors may also be good candidates for combination therapy with other anti-cancer agents." (PMID 35158821, 2022).